KRTAP25-1 (keratin associated protein 25-1)
Description:
In the hair cortex, hair keratin intermediate filaments are embedded in an interfilamentous matrix, consisting of hair keratin-associated proteins (KRTAP), which are essential for the formation of a rigid and resistant hair shaft through their extensive disulfide bond cross-linking with abundant cysteine residues of hair keratins. The matrix proteins include the high-sulfur and high-glycine-tyrosine keratins (By similarity).
Synonyms: KAP25.1
Tractability: Antibody: the Human Protein Atlas places it where antibodies can reach.
Gene: Protein-coding gene on chromosome 21 (30,289,145 to 30,289,514, reverse strand). Ensembl gene ENSG00000232263.
Subcellular location (Human Protein Atlas): Nuclear membrane; Cytosol; Plasma membrane
Pathways (Reactome):
Developmental Biology: Keratinization
Gene Ontology:
Molecular function: structural molecule activity
Cellular component: cytosol; keratin filament
Genetic constraint (gnomAD): Loss-of-function variants: 2 observed, 1.44 expected, observed/expected ratio (o/e) 1.39, 90% interval 0.44 to 1.92. That is too few expected variants to judge how well the gene tolerates losing a copy. Missense variants: 136 observed, 126.31 expected, observed/expected ratio (o/e) 1.08, 90% interval 0.94 to 1.24. Synonymous variants: 47 observed, 42.6 expected, observed/expected ratio (o/e) 1.1, 90% interval 0.87 to 1.41.
Homologues: Orthologues: chimpanzee KRTAP25-1 (96% identical), dog KRTAP25-1 (52% identical). Paralogues in human: KRTAP13-1 (32% identical), KRTAP13-2 (32% identical), KRTAP13-3 (31% identical), KRTAP13-4 (28% identical), KRTAP15-1 (25% identical), KRTAP11-1 (24% identical), KRTAP26-1 (21% identical), KRTAP27-1 (17% identical).